RN7SL417P (RNA, 7SL, cytoplasmic 417, pseudogene)
Gene: Miscellaneous RNA gene on chromosome 15 (84,394,072 to 84,394,336, forward strand). Ensembl gene ENSG00000244056.
Homologues: Orthologues: pig Metazoa_SRP (54% identical). Paralogues in human: RN7SL736P (92% identical), RN7SL214P (86% identical), RN7SL536P (84% identical), Metazoa_SRP (84% identical), RN7SL106P (84% identical), RN7SL238P (84% identical), RN7SL545P (84% identical), RN7SL759P (84% identical), RN7SL196P (83% identical), RN7SL286P (83% identical), RN7SL539P (83% identical), RN7SL796P (83% identical), and 705 more.